MROH7 (maestro heat like repeat family member 7)
Synonyms: C1orf175; HEATR8; FLJ46354
Tractability: Antibody: UniProt predicts a signal peptide or a membrane-spanning region. PROTAC: its protein half-life has been measured.
Gene: Protein-coding gene on chromosome 1 (54,641,754 to 54,710,266, forward strand). Ensembl gene ENSG00000184313.
Subcellular location: Membrane
Gene Ontology:
Cellular component: extracellular region; cytoplasm; membrane
Genetic constraint (gnomAD): Loss-of-function variants: 106 observed, 126.56 expected, observed/expected ratio (o/e) 0.84, 90% interval 0.71 to 0.98. The upper end of that interval is the gene's LOEUF score, 0.98, which puts it in group 4 of 6, group 1 being the genes least tolerant of losing a copy. Missense variants: 1,586 observed, 1,729.9 expected, observed/expected ratio (o/e) 0.92, 90% interval 0.88 to 0.96. Synonymous variants: 655 observed, 698.27 expected, observed/expected ratio (o/e) 0.94, 90% interval 0.88 to 1.
Homologues: Orthologues: chimpanzee MROH7 (98% identical), macaque MROH7 (95% identical), pig MROH7 (80% identical), rabbit MROH7 (79% identical), rat Mroh7 (70% identical), mouse Mroh7 (69% identical), guinea pig MROH7 (65% identical), dog MROH7 (59% identical). Paralogues in human: MROH1 (19% identical), MROH5 (19% identical), MROH8 (18% identical), MROH2A (16% identical), MROH2B (16% identical), MROH6 (15% identical), MROH9 (12% identical), MRO (4% identical).
Diseases named in the same sentence as MROH7 in open-access papers:
MROH7 is named in the same sentence as 1 disease in open-access papers, as found by Europe PMC text mining. Sharing a sentence is not in itself a finding about the gene and the disease. The quoted sentences say what the papers report.
dystocia (1 paper, 2020). Slow or difficult obstetric labor or childbirth. "Previous studies reported that CDCP2, ENSBTAG00000030623 and MROH7 were located within two QTL for body weight and dystocia in Holstein cattle and PCDH8 in a QTL for marbling score in Angus cattle." (PMID 33167870, 2020).